RN7SL518P (RNA, 7SL, cytoplasmic 518, pseudogene)
Gene: Miscellaneous RNA gene on chromosome 10 (76,242,022 to 76,242,301, reverse strand). Ensembl gene ENSG00000265486.
Homologues: Orthologues: chimpanzee Metazoa_SRP (99% identical), macaque Metazoa_SRP (93% identical). Paralogues in human: RN7SL1 (87% identical), RN7SL2 (87% identical), RN7SL3 (86% identical), RN7SL664P (85% identical), RN7SL630P (84% identical), RN7SL47P (83% identical), RN7SL509P (83% identical), RN7SL709P (83% identical), RN7SL147P (83% identical), RN7SL326P (83% identical), RN7SL732P (83% identical), RN7SL357P (82% identical), and 710 more.